IL6 (interleukin 6)
Diseases named in the same sentence as IL6 in open-access papers (continued):
Sharing a sentence is not in itself a finding about the gene and the disease.
astrocytoma (continued). "Thus, the Aβ protein of the plaques is said to potentiate the secretion of IL-6 and IL-8 by IL-1β-activated astrocytoma cells, of IL-6 and TNF-α by lipopolysaccharide- (LPS-) stimulated astrocytes, and of IL-8 by monocytes." (PMID 22566778, 2012). "The secretion of tumour necrosis factor-α (TNFα),interleukin-1α (IL-α) and interleukin-6 (IL-6) by ahuman astrocytoma cell fine was studied 1 h, 3 h, 6 h and 24 h afterinfection with tachyzoites from three Toxoplasma gondiistrains (virulent, RH; cystogentc, 76K and Prugniaud strains)." (PMID 18472955, 1994). "Low MeHg concentrations (up to 5 μM) activate interleukin-6 (IL-6) and monocyte chemoattractant protein (MCP)-1 expression in the human astrocytoma cell line U87MG." (PMID 39567405, 2025). "Previous work using the selective antagonist NF340 as well as a CRISPR/Cas9 knockout control had identified IL-6 and IL-8 as bona fide targets of the recombinant P2Y11 receptor in the astrocytoma 1321N1 cell line." (PMID 37016172, 2023). "LPS stimulates astrocytes to secrete cytokines including IL-6 and TNF-α, activates astrocytoma cells to secrete IL-6 and IL-8 and monocytes to secrete IL-8 under the influence of Aβ peptides." (PMID 34685770, 2021). "Plasma IL-6 and YKL-40 levels were elevated in GBM compared to astrocytoma WHO grade II-III (AII-III) patients (p = 0.036; p = 0.0003)." (PMID 32363159, 2020). "Both plasma IL-6 and YKL-40 levels were higher in GBM compared to astrocytoma WHO grade II-III, but this effect disappeared when corrected for age." (PMID 32363159, 2020). "Our results obtained with the human astrocytoma cell line U87 show the effective induction of NGF and IL-6 by PRP/NP." (PMID 25841889, 2015). "In the present study, our results further confirmed inhibition of IL-6 and IL-8 secretion of conditioned media from senescent astrocytic CRT cells could abrogate the stimulation of astrocytoma cell lines (U373-MG, U87-MG and U251-MG)." (PMID 28891967, 2017). "The medulloblastoma and ependymoma cultures and tissues also secreted IL-6, IL-8 and IL-15, while the astrocytoma culture secreted no or very low levels of these interleukins." (PMID 26183281, 2015). "Cell-based studies in 1321N1 astrocytoma cells, which lack functional P2Y6 receptors, showed that exogenous expression of P2Y6 induces a robust, receptor- and agonist-dependent secretion of inflammatory mediators IL-8, IL-6, MCP-1 and GRO1." (PMID 25360548, 2014).
cerebrovascular disease (36 papers, 2014 to 2026). "Participants in the high IL‐6 subgroup also exhibited a stronger association between cerebrovascular disease and levels of NfL and GFAP than those in the low IL‐6 subgroup." (PMID 38717935, 2024). "By inhibiting microtubule polymerization and suppressing the NLRP3 inflammasome, colchicine reduces the production of pro-inflammatory cytokines such as interleukin-1β and interleukin-6, both of which have been implicated in the pathogenesis of cerebrovascular disease." (PMID 41407975, 2025). "Interleukin-6, a proinflammatory cytokine implicated in cerebrovascular disease and CVD binds A2M." (PMID 39761918, 2025). "Additionally, elevated levels of pro-inflammatory cytokines, including tumor necrosis factor α (TNF-α) and interleukin 6 (IL-6), in these patients are linked to vascular damage and an increased risk of cardiovascular and cerebrovascular diseases." (PMID 39596351, 2024). "Elevated serum IL‐6 is associated with a high risk of cerebrovascular diseases." (PMID 34792838, 2022). "Proinflammatory SASP factors, such as interleukin 6 (IL-6) and interleukin 1β (IL-1β), are upregulated during aging and cerebrovascular diseases." (PMID 36599934, 2023). "Currently, direct evidence concerning IL-6 inhibition on the alleviation of Cerebrovascular Diseases is scarce, but based on the findings described in the previous section, IL-6 is significantly elevated during IS and is involved in the development of IS." (PMID 34504432, 2021). "For death outcome, IL-6, co-existing cerebrovascular disease, prothrombin time activity, and urea nitrogen were independent risk factors." (PMID 33693017, 2021). "Predictors of mortality were older age (P = 0.001), antecedents of cerebrovascular disorders (P = 0.034), previous use of oral anticoagulants (P = 0.009) or selective serotonin reuptake inhibitors (P = 0.003), and increased levels of interleukin-6 (P = 0.001)." (PMID 33041811, 2020). "Although VD results from cerebrovascular disease, studies have indicated that chronically elevated high sensitivity C-reactive protein (CRP) and the combination of elevated high sensitivity CRP and interleukin-6 due to inflammation are associated with an increased rate of VD." (PMID 40305494, 2025). "Since IL-6 is a very important mediator that is one of inflammatory cytokines in CNS and leads to inflammatory damage, thus, it is reasonable to infer that IL-6 has significant implications for the prevention and treatment of Cerebrovascular Diseases such as IS." (PMID 34504432, 2021). "Likewise, in Cerebrovascular Diseases, IL-6 may play a vital role in the diagnosis and prognosis of IS and could be used to predict the size of brain damage." (PMID 34504432, 2021). "In the liver, CRP production is triggered by IL-6, and elevated CRP has toxic effects on endothelial cells and raises the permeability of the BBB, thus enhancing the development of neurodegenerative and cerebrovascular diseases." (PMID 36675440, 2023). "CRP, one of the acute response phase proteins, can reflect the level of inflammation in the body and the progress of cerebrovascular disease; TNF-α and IL-6 are proinflammatory factors, both of which can promote the chemotaxis and adhesion of inflammatory factors, and adversely affect patients." (PMID 35692885, 2022). "We incorporated 21 items with relatively high AUC into a multivariable model and found that cerebrovascular disease (CVD; HR, 6.162), prothrombin activity (PTA; HR, 0.912), blood urea nitrogen (BUN; HR, 1.207), and IL-6 (HR, 1.085) were independent predictors for fatality." (PMID 33693017, 2021).
alcoholic liver diseases (35 papers, 2012 to 2026). A disorder caused by damage to the liver parenchyma due to alcohol consumption. "Other factors include diminished hepatic extraction, effects of cytokines (IL-6), and the inherent effect of alcohol itself in those with alcoholic liver disease, which can interfere with zinc absorption." (PMID 40400889, 2025). "IL-6 and IL-10 are cytokines with anti-inflammatory and hepatoprotective roles, e.g., in alcoholic liver disease (ALD)." (PMID 40415790, 2025). "In alcoholic liver disease, inhibition of IL-6 has been demonstrated to reduce serum AST levels and attenuate ethanol-induced liver damage." (PMID 38139043, 2023). "Cytokines, namely IL-6, IL-10, and TNF-α, are strongly associated with the development of alcoholic liver diseases according to previous research." (PMID 37759693, 2023). "The results in our study were consistent with other studies that found blood IL-6 increased with increasing severity of alcoholic liver disease." (PMID 38162671, 2023). "It is suggested that the mechanism of exercise-induced improvement of alcoholic liver disease is mediated by the IL-6–p47phox oxidative-stress pathway." (PMID 35455983, 2022). "In summary, Klotho, MDA, IL-8, and IL-6 behave similarly in patients with alcoholic liver disease, being more or less intensely related to disease progression and liver function impairment." (PMID 36009045, 2022). "Our research group reviewed the role of IL-6 in alcoholic liver disease and determined the relationship between IL-6 and p47phox." (PMID 35455983, 2022). "During the development of alcoholic liver disease, hepatic production of proinflammatory cytokines including IL-6, tumor necrosis factor (TNF)-α, and TNF-like weak inducer of apoptosis (TWEAK) is significantly increased." (PMID 27547491, 2014). "These previous findings indicate that LAB treatment inhibits the production of IL-6, IL-12, and MCP-1, as well as the accumulation of lipid droplets that cause alcoholic liver damage, suggesting they could play a role in alleviating ALD." (PMID 36081800, 2022). "In this regard, the strongest associations with respect to the odds ratios were observed in the presence of alcoholic liver disease (OR = 2.70, 95% CI = 1.41–5.15), hemoglobin (OR = 0.57, 95% CI = 0.47–0.70), and IL-6 concentration (OR = 2.44, 95% CI = 1.22–4.76)." (PMID 32357568, 2020). "Moreover, our results herein are also consistent with the observations from other studies indicating that the progression and severity of alcoholic liver disease is correlated with increased IL-6 levels and induction of hepatic lipogenesis." (PMID 26035386, 2015). "Among the top 30 genes in the gene regulatory network, 7 genes are enriched in alcoholic liver disease (hsa04936), including TNF, IL6, IFNA1, CYP2E1, ALDH2, ADH1B, ADH1C." (PMID 38429802, 2024). "We found that 11 genes such as IL-6, TLR4, TNF, and CASP3 were interactive targets between GRg1 and ALD, suggesting that GRg1 protected alcoholic liver damage through these targets." (PMID 36052161, 2022). "Proinflammatory cytokines like IL-6 and TNF-α play a significant role in the pathogenesis of alcoholic liver disease." (PMID 36230090, 2022). "Alcoholic liver disease stimulates the release of cytokines, such as TNF-α, interleukin-1β (IL-1β) and IL-6, which promote the production RANKL and osteoclastogeneis." (PMID 32151025, 2020). "Upregulation of Nogo-B was also found in HCCs to stimulate the IL-6/STAT3 pathway and alcoholic liver disease through the regulation of M1 polarization of Kupffer cells." (PMID 31358770, 2019). "Gut-derived LPS recruits macrophages via TLR4 to overexpress inflammatory cytokines such as IL-6, TNF-α, which contribute to the inflammatory processes in alcoholic liver disease." (PMID 31116255, 2019). "In alcoholic liver disease, gut-derived LPS stimulate hepatic macrophages to produce TNF-α, interleukin-6 (IL-6), and interleukin-1β (IL-1β), which exacerbate liver injury." (PMID 25978374, 2015).
alcoholic liver diseases (continued). "Moreover, in an animal model of alcoholic liver disease, L. plantarum could reduce serum TNF-α, IL-6, LPS, and hepatic malondialdehyde levels as compared with those in alcohol-fed rats alone." (PMID 39200311, 2024).
glomerulosclerosis (34 papers, 1993 to 2025). A hardening of the kidney glomerulus caused by scarring of the blood vessels. "IL-6 is also enhanced in the serum of Sgpl1-deficient mice, which develop glomerulosclerosis and tubular atrophy." (PMID 36834691, 2023). "These include renal tubulointerstitial fibrosis and glomerulosclerosis, as well as arteriosclerosis, amyloid deposition, and renal inflammaging caused by oxidative stress and proinflammatory cytokines, including interleukin-6 and tumor necrosis factor-α." (PMID 35646947, 2022). "Stimulation of HRMC with IL‐6 enhanced their proliferation and the expression of glomerulosclerosis‐associated fibronectin and collagen IV via signal transducer and activator of transcription 3 (STAT3) activation." (PMID 33043579, 2020). "HDL-C can suppress the release of pro-inflammatory mediators like tumor necrosis factor-α and interleukin-6 while enhancing superoxide dismutase activity to alleviate oxidative stress, delaying glomerulosclerosis and tubulointerstitial fibrosis." (PMID 40483478, 2025). "When renal function is impaired, the glomerular mesangial cells produce a large amount of interleukin-6 (IL-6), interleukin-1β (IL-1β), and other inflammatory mediators, exacerbating glomerulosclerosis and renal function decline." (PMID 36615439, 2022). "Cola drinking treatment induced glomerulosclerosis (+21%, p < 0.05), higher histopathological score (+13%, p < 0.05), and largely higher tubular expression of both IL-6 (7-fold, p < 0.001) and TNF-α (4-fold, p < 0.001)." (PMID 27340342, 2016). "The subsequently release of pro-inflammatory cytokines such as TNF-α (Tumour Necrosis Factor alpha), IL-6 (Interleukin 6), and TGF-β (transforming growth factor-beta) by the mesangial cells can induce the inflammation and glomerulosclerosis and eventually cause renal injury." (PMID 36238099, 2022). "IL-6 can stimulate the adhesion, proliferation and differentiation of glomerular mesangial cells of under synergistic action of other cytokines, which in turn lead to glomerular sclerosis." (PMID 31684904, 2019). "Clinical and experimental studies have demonstrated the role of lipoproteins in the decline of renal function with emphasis on glomerulosclerosis, neutrophil and macrophage infiltration and upregulation of the cytokine interleukin (IL)-6 or endothelial nitric oxide synthase." (PMID 18949085, 2007). "The heightened synthesis of IL-6 in the glomerulus may act to stimulate the local proliferation and differentiation of mesangial cells, thereby contributing to the complex processes leading to fibrosis and glomerulosclerosis." (PMID 38787228, 2024). "Thus, IL6 over-reactivity may induce mesangial dysfunction, increase cell proliferation, increase mesangial matrix deposition, and glomerular sclerosis." (PMID 33967827, 2021). "Cytokines and chemokines released during inflammation (e.g., IL-6 and TNF-α) directly damage glomerular and tubular cells and promote mesangial cell proliferation and matrix deposition, ultimately leading to glomerulosclerosis." (PMID 40130253, 2025). "And dietary fiber can promote the production of SCFAs, which can reduce inflammation levels such as IL-6 and TNF-α, alleviate fibrosis-promoting factors such as collagen and TGF-β, and fight against glomerulosclerosis." (PMID 37362429, 2023). "We observed that several components of SASP known to play a potential role in glomerulosclerosis, such as PAI‐1, IL‐1β, IL‐6, or MMP13, were upregulated in kidneys of old mice as compared to young mice." (PMID 34725920, 2021). "Inflammatory cytokines such as IFN γ, IL-6, and TNF overactivated STAT1, STAT3, and NF-κB transcription factors to promote glomerulosclerosis and renal interstitial fibrosis." (PMID 34194519, 2021). "Netrin-1 also suppressed AKI-induced tubular atrophy, interstitial fibrosis, vascular dropout, and glomerular sclerosis through suppression of STAT3 and JNK signaling and IL-6 expression in tubular epithelial cells." (PMID 27176224, 2016).
glomerulosclerosis (continued). "In addition, suppression of IL-6/STAT3 signaling suppressed acute kidney injury-induced interstitial fibrosis and glomerulosclerosis." (PMID 35491874, 2022).
keratoconus (34 papers, 2010 to 2026). A degenerative, structural disorder of the eye, characterized by a cone-shaped protrusion of the cornea. "IL-6 has also been found to be correlated with keratoconus severity, with increasing IL-6 concentrations in tear samples associated with more severe keratoconus." (PMID 37374145, 2023). "These genes were also associated with elevated inflammatory cytokine IL-6 in the corneal epithelium and in the tears of keratoconus patients." (PMID 27493978, 2016). "For instance, analysis of tear film components in keratoconus has revealed candidate biomarkers: elevated levels of certain cytokines (IL-6, TNF-α), MMPs, and specific microRNAs." (PMID 41595486, 2026). "The use of Spearman correlation matrices further revealed stronger and more coordinated cytokine co-regulation in the stable keratoconus group compared to healthy controls, particularly involving IL-6, IL-1β, and TNF-α." (PMID 40980981, 2025). "Stable keratoconus patients displayed stronger positive correlations among multiple cytokines, particularly IL-6, IL-1β, and TNF-α, indicating a more coordinated inflammatory network." (PMID 40980981, 2025). "In fact, proinflammatory cytokines (IL-1, IL-6, TNF-α, and TGF-β), oxidative stress, or degradation of collagens by metalloproteases (MMP-1, MMP-3, and MMP-9) has been implicated in keratoconus pathophysiology." (PMID 35075374, 2022). "Several pro-inflammatory markers such as Interleukin-6 (Il-6) and Tnfα, along with matrix metalloproteinase 9 (Mmp9) are elevated in the tear fluid of keratoconus patients." (PMID 31569699, 2019). "Enzyme linked immunosorbent assay (ELISA) analysis of capillary collected tears in 28, 30 and 94 patients with keratoconus in three different studies showed elevated levels of inflammatory markers IL-6, TNFα and MMP9." (PMID 27493978, 2016). "They observed increased levels of MMP-9, tumor necrosis factor, and interleukin-6 in the tear film of patients with keratoconus and overexpression of IL-6 and TNF-alpha in the tears of subclinical keratoconic patients." (PMID 27563164, 2016). "There were no significant levels of proinflammatory serum cytokines, in contrast to increased levels of IL-6 and IL-17 in the tear film of keratoconus patients." (PMID 27563164, 2016). "Comparing tear fluid cytokines in the control and keratoconus subjects, we noted an increase in IL-6 in keratoconus, in agreement with earlier reports." (PMID 21298010, 2011). "More recently, Lema and Durán targeted specific cytokines, cell adhesion molecules, and proteases in patients with keratoconus, and found levels of IL-6, TNF-α, and MMP-9 higher in keratoconus subjects as compared to normals." (PMID 21031023, 2010). "Recent studies have also suggested a correlation between the development of keratoconus and the inflammatory status of the cornea, as evidenced by elevated levels of inflammatory cytokines such as interleukin-6 (IL-6) and tumor necrosis factor-α in patients’ tears." (PMID 39869570, 2025). "Furthermore, this study did not measure other biochemical factors potentially involved in the pathogenesis of keratoconus, such as IL-6 and MMP-9." (PMID 40547926, 2025). "Keratoconus, with a similar inflammatory profile to that of ocular surface disease, has elevated Interleukin (IL)-1β, IL-6, tumor necrosis factor (TNF)-α, and matrix metalloproteinase (MMP)-9, contributing to extracellular matrix degradation and stromal thinning." (PMID 40993744, 2025). "Numerous studies have identified altered cytokine expression in the tear fluid and corneal epithelium of keratoconus patients—particularly IL-6, TNF-α, and IL-1 family members—supporting a model of localized inflammation contributing to stromal degradation and extracellular matrix remodeling." (PMID 40980981, 2025). "Analyses of tears and corneal tissue in patients with keratoconus have shown an increase in several cytokines, including IL-6, IL-8, IL-1β, TNF-α, and IFN-β, which may support this hypothesis." (PMID 38203537, 2023).